FAAH (fatty acid amide hydrolase)
Diseases named in the same sentence as FAAH in open-access papers (continued):
Sharing a sentence is not in itself a finding about the gene and the disease.
Alzheimer disease (21 papers, 2012 to 2025). A progressive, neurodegenerative disease characterized by loss of function and death of nerve cells in several areas of the brain leading to loss of cognitive function such as memory and language. "FAAH is also closely associated with Aβ deposition, suggesting that it plays a regulatory role in microglial function in Alzheimer’s disease-related pathological changes." (PMID 40076984, 2025). "Reduced DNA methylation at the FAAH gene promoter (responsible for encoding FAAH) has been reported in late-onset Alzheimer’s disease." (PMID 37298078, 2023). "Caffeine inhibits brain fatty acid amide hydrolase and decreases amyloid-beta accumulation, thus reducing susceptibility to neurodegenerative conditions like Alzheimer’s disease." (PMID 38024372, 2023). "Endocannabinoids such as AEA and CB2 receptors and enzymes such as fatty acid amide hydrolase (FAAH) influence retrograde signalling (observed in Alzheimer’s disease) in the brain." (PMID 38002684, 2023). "In recent studies, FAAH was found to be overexpressed in perivascular astrocytes of cortical SIV tissue samples and neuritic plaque-associated astrocytes in Alzheimer’s disease brains." (PMID 35269478, 2022). "Previous human studies have already reported alterations in DNA methylation at the FAAH promoter in Alzheimer’s Disease and alcoholism." (PMID 36499556, 2022). "An enhanced MAGL enzymatic activity coupled with upregulation of FAAH has been observed through a post-mortem of patients’ brains with Alzheimer’s disease." (PMID 35009027, 2021). "For example, reduced DNA methylation at the FAAH gene was found in a study of late-onset Alzheimer’s disease, resulting in increased FAAH protein activity." (PMID 33494322, 2021). "The mRNA and protein levels and protein activity of FAAH are increased in late-onset (age > 65) Alzheimer’s disease (LOAD) patients." (PMID 32433545, 2020). "In accordance to previous reports in Alzheimer disease we found in primary cell cultures, low FAAH expression in fibrillary and high FAAH expression in protoplasmic astrocytes." (PMID 22457773, 2012). "Inhibition of fatty acid amide hydrolase (FAAH), which degrades endogenous cannabinoids, may also be of great importance in the treatment of Alzheimer’s disease." (PMID 40283681, 2025). "Notably, patients with the most severe cognitive impairment exhibited the lowest levels of methylation, suggesting FAAH as a potential therapeutic target for Alzheimer’s disease." (PMID 37298078, 2023). "Moreover, enhanced MAGL enzymatic activity and increased FAAH expression and activity have been observed postmortem in human Alzheimer's disease brain." (PMID 32508955, 2020). "Fatty acid amide hydrolase (FAAH) is an enzyme that breaks down endocannabinoids like anandamide (AEA) and may provide beneficial effects in a mouse model of Alzheimer’s disease (AD)-like pathology." (PMID 40806215, 2025). "Their subsequent study revealed that the exaggerated inflammatory response of FAAH depletion was mediated by IL-1β specifically in the transgenic Alzheimer’s disease model but not in wild type animals." (PMID 31121907, 2019). "For instance, FAAH-1 activity and expression are up-regulated in Alzheimer’s disease patients, unlike any other ECS element analyzed (including CB1, CB2, and NAPE-PLD)." (PMID 28611591, 2017). "Activation of CB2R and neuroprotection by beta-caryophyllene combined with the reduction of FAAH and MAGL activity by lavender essential oil support a hypothesis that using these oils therapeutically may modulate the brain's innate response and reduce Alzheimer's disease progression." (PMID 32508955, 2020).
breast carcinoma (18 papers, 2011 to 2025). "FAAH gene polymorphism was reported to be associated with postoperative pain sensitivity in female patients with breast cancer." (PMID 36702852, 2023). "Increased FAAH expression has been associated with poor patient survival in prostate and breast cancer." (PMID 24811863, 2014). "The evidence gathered in this study reveals the profound importance of FAAH in the differentiation dynamics of MECs in the adult mammary gland, and raises potentially important implications for the pathogenesis of breast cancer." (PMID 38184644, 2024). "Regarding the first scenario, it is well-known that PEA and OEA, two FAAH substrates, can downregulate the expression and activity of FAAH in breast cancer cells." (PMID 38184644, 2024). "While the role of FAAH in endocannabinoid-mediated nociception for breast cancer has been studied, its role in cancer growth and progression has not been examined." (PMID 37921652, 2023). "To shed some light on the molecular mechanisms of FAAH action on BC progression, we analyzed the expression of a panel of 84 BC-associated genes in MMTV-neu:FAAH+/+ and−/− mice using the commercial RT2 ProfilerTM PCR Array of Mouse Breast Cancer." (PMID 37253733, 2023). "This study explores the functional relevance and therapeutic potential of FAAH inhibition combined with the proapoptotic activity of exogenous endocannabinoids on breast cancer survival." (PMID 37921652, 2023). "In this regard, it has been described that PEA enhances the anti-proliferative effects of ANA on human breast cancer cells by inhibiting the expression of FAAH." (PMID 21854612, 2011). "Aside from the insight provided into the potential role of FAAH in breast cancer, our findings may have translational relevance on their own." (PMID 38184644, 2024). "Increased expression of FAAH by the breast cancer cell lines may allow for evasion of the apoptosis cascade." (PMID 37921652, 2023). "FAAH inhibition was more effective than exogenous endocannabinoid treatment, and the combination of FAAH inhibitors and endocannabinoids was the most effective in inducing apoptosis of breast cancer cells in vitro." (PMID 37921652, 2023). "High levels of FAAH were observed in different breast cancer cell lines." (PMID 37921652, 2023). "For example, FAAH is known to be upregulated in prostate, pancreatic, colon and breast cancer." (PMID 25594019, 2014). "Similarly, FAAH functions as a metastasis suppressor, and its high expression correlates with worse outcomes in luminal breast cancer, suggesting its inhibition could enhance anti-tumor effects." (PMID 40227503, 2025). "In addition, in vivo FAAH inhibition reduced breast cancer growth in immunodeficient mice." (PMID 37921652, 2023). "In addition, GGH accumulation may reflect a functional correlation with FAAH expression, which could play a role in the progression of breast carcinoma." (PMID 23374458, 2013). "In contrast, the degradation of lipids by fatty acid amide hydrolase (FAAH) prevents tumor progression and lung metastasis both in vitro and in vivo, and FAAH serves as a biomarker for longer survival in breast cancer patients." (PMID 39695088, 2024). "Although the research on PEA in breast cancer is still in its infancy, an in vitro study using human breast cancer cells showed that PEA inhibited the activity of fatty acid amide hydrolase, the enzyme responsible for the degradation of AEA." (PMID 39433509, 2024). "With URB597, the other FAAH inhibitor used, decreases in cell viability were similarly visualized in the MDA-MB-231 breast cancer cell line." (PMID 37921652, 2023). "Western blot analysis confirmed the presence of elevated FAAH in the T47D and MCF7 breast cancer cell lines, especially in the T47D cell line." (PMID 37921652, 2023).
breast carcinoma (continued). "One of the early pioneering studies in this field showed that arachidonoyl trifluoromethyl ketone, an inhibitor of the major AEA-degrading enzyme FAAH, enhanced the antiproliferative effect of exogenously added AEA on breast cancer cell lines." (PMID 34830856, 2021). "cPLA2, FAAH and COX2 were demonstrated to be present in MCF-7 breast cancer cells by western blot analyses." (PMID 22692672, 2012). "Breast cancer tissues were also found displaying over-expression of γ-glutamyl hydrolase (GGH) and fatty acid amide hydrolase (FAAH) and underexpression of TAF5-like RNA polymerase II p300/CBP-associated factor (PCAF)-associated factor 65 kDa subunit 5L (TAF5L)." (PMID 24550697, 2014). "Four percent of the FAAH protein expression was positive in non-cancerous breast tissues whereas 89% of the breast cancer tissues expressed FAAH (χ2 = 19.3, P < 0.001)." (PMID 23374458, 2013). "Therefore, it could be argued that, by regulating MEC plasticity in the normal mammary gland, FAAH could be involved in the early stages of HER2/neu-induced tumorigenesis, and probably other breast cancer subtypes." (PMID 38184644, 2024). "In breast cancer cell lines, when the optimal RG combinations SF1 + TRA2B + THRAP3 + RHOA + QRICH1, SF1 + TRA2B + THRAP3, or THRAP3 + RHOA + QRICH1 were used for normalization, the expression of FAAH was highest in MCF-7 cells, followed by MCF-10A cells, and was least in MDA-MB-231 cells." (PMID 34895237, 2021).
prostate carcinoma (18 papers, 2010 to 2023). A carcinoma that arises from epithelial cells of the prostate gland. "In conclusion, the present study has demonstrated that tumour epithelial FAAH-IR is associated with prostate cancer severity and outcome." (PMID 20808855, 2010). "FAAH is upregulated in a variety of tumors, such as prostate cancer, and its inhibition results in similar antiproliferative and antimetastatic effects." (PMID 37024452, 2023). "High expression of FAAH was reported to promote cell invasion and migration by hydrolysing 2-arachidonoylglycerol in prostate cancer." (PMID 36702852, 2023). "FAAH is overexpressed in prostate cancer cell lines and tumor tissues; tumor FAAH immunoreactivity (FAAH-IR) is positively correlated with disease severity for cases with mid-range CB1 expression." (PMID 36291926, 2022). "Functional studies have shown that downregulation of FAAH in prostate cancer cells attenuates 2-AG hydrolysis and cell invasion, and the phenotypic effects can be reversed by FAAH overexpression." (PMID 36291926, 2022). "In contrast, rat Dunning AT1 prostate cancer cells express FAAH, and AEA uptake into these cells is reduced upon FAAH inhibition." (PMID 28910408, 2017). "Conversely, FAAH transfection of human androgen-insensitive PC-3 prostate cancer cells, which normally express low levels of this enzyme, increases their invasivity in the same system." (PMID 28910408, 2017). "In prostate cancer cells, FAAH was overexpressed, and the upregulated FAAH levels correlated with poor patient prognosis." (PMID 29066974, 2017). "The limited data published in this field were obtained using prostate carcinoma cells whose invasion was inhibited by 2-AG, a specific FAAH inhibitor or by siRNA targeting FAAH." (PMID 26930716, 2016). "Human PC-3 prostate cancer cells have a very low level of FAAH activity and are thus useful in this respect." (PMID 24466356, 2014). "The effects of FAAH inhibition upon AEA uptake were investigated in four cell lines: AT1 rat prostate cancer, RBL-2H3 rat basophilic leukaemia, rat C6 glioma and mouse P19 embryonic carcinoma cells." (PMID 25078278, 2014). "A recent report showed that FAAH is also over-expressed in prostate cancer cells and the inhibition of FAAH can enhance the survival of cancer patient." (PMID 25115386, 2014). "Here we have investigated the expression of the endocannabinoid metabolising enzyme fatty acid amide hydrolase (FAAH) in a well characterised tissue microarray from patients diagnosed with prostate cancer at transurethral resection for voiding problems." (PMID 20808855, 2010). "With respect to FAAH, it has been reported that in a commercially available tissue microarray, cores from prostate cancer tissues had a higher expression of the enzyme than seen in normal tissue." (PMID 20808855, 2010). "These authors found a low incidence of FAAH-IR in normal tissue (1 of 8 cores) whereas a FAAH expression was seen in 109 of 157 cores for cases of prostate cancer." (PMID 20808855, 2010). "Inhibitor 51 was further investigated in competitive ABPP: at 0.1 μM, 51 inhibited ABHD11 in all tested proteomes (mouse whole brainmembranes, prostate cancer cell lysates, and mitochondrial fractionof brown fat and testicle), but at higher concentrations (1–10μM) it also inhibited FAAH." (PMID 34213320, 2021). "In addition to antiproliferative properties, the FAAH inhibitor CAY10401 decreased prostate cancer cell invasion." (PMID 31143113, 2019). "Accordingly, higher expression levels of FAAH have been found in prostate cancer tissue." (PMID 31143113, 2019). "Although R-flurbiprofen failed in phase II clinical studies of prostate cancer, its positive results may encourage testing of FAAH-based combi-treatments for pain and cancer." (PMID 26875980, 2016). "Also, overexpression of FAAH was found to be sufficient to increase migration and invasion in prostate cancer cells." (PMID 24811863, 2014).
prostate carcinoma (continued). "Moreover, inactivation of FAAH activity has been shown to potentiate the anti-tumorigenic effects of AEA in prostate cancer." (PMID 24811863, 2014). "Ketoconazole may be useful as a template for the design of dual-action FAAH/CYP17 inhibitors as a novel strategy for the treatment of prostate cancer." (PMID 24466356, 2014). "In addition, FAAH expression has been demonstrated in the prostate cancer cell lines (PC-3, DU-145, and LNCaP) and human prostate cancer tissues." (PMID 24369462, 2013). "We confirmed the presence of IL-4 IR in prostate cancer epithelial tissue, and found that incubation of both human androgen-insensitive PC-3 cells and rat Dunning R3327 AT-1 prostate cancer cells with IL-4 for 24 h produced a significant increase in FAAH activity of the cells." (PMID 20808855, 2010). "Those authors concluded that “inhibition of FAAH activity by specific inhibitors may be one therapeutic target for the treatment of prostate cancer”." (PMID 20808855, 2010). "Tumour epithelial FAAH-IR is associated with prostate cancer severity and outcome at mid-range, but not high, CB1IR scores." (PMID 20808855, 2010). "Very little work has been undertaken on the uptake of AEA into prostate cancer cells, but PC3 cells, which express low levels of FAAH, unsurprisingly do not shown this phenomenon, with uptake in the absence and presence of FAAH inhibitors being very similar." (PMID 28910408, 2017). "Interleukin-4 (IL-4) receptor IR was found on tumour epithelial cells and incubation of prostate cancer PC-3 and R3327 AT1 cells with IL-4 increased their FAAH activity." (PMID 20808855, 2010). "The relative importance of FAAH and MGL in the metabolism of 2-AG has been investigated in prostate cancer cells." (PMID 20808855, 2010). "The TH2 cytokine interleukin-4 (IL-4), which has been reported to regulate FAAH and CB1 receptors in lymphocytes and Jurkat cells, is involved the pathogenesis of several cancer types, including prostate cancer." (PMID 20808855, 2010). "Similarly, the FAAH inhibitor CAY10401 can reduce cell invasion in LNCaP cells, a prostate carcinoma cell line." (PMID 37024452, 2023). "In addition, anti-invasive properties on prostate carcinoma cells have been described for CAY10401, a specific FAAH inhibitor, and for FAAH siRNA." (PMID 26930716, 2016). "Recently, an increase in FAAH expression in prostate cancer cell has been reported when compared to that in the noncancerous prostate cell." (PMID 24369462, 2013). "FAAH immunoreactivity (FAAH-IR) was assessed in formalin-fixed paraffin-embedded non-malignant and tumour cores from 412 patients with prostate cancer." (PMID 20808855, 2010). "It is well known that the tumour microenvironment plays an important role in the pathogenesis of prostate cancer, and it can be hypothesised that a component of the tumour microenvironment regulates in the same manner the activity of both CB1 receptors and FAAH." (PMID 20808855, 2010). "None of these molecules have been investigated in prostate cancer cells with respect to FAAH." (PMID 20808855, 2010). "DU-145 prostate cancer cells respond to TNF-α treatment with an increased expression of PTGS2, of COX-2 and of PGE2 production and this is accompanied by a decreased expression of NAPEPLD without change in NAAA or FAAH expression, thereby producing an imbalance in PTGS2/NAPEPLD." (PMID 33172176, 2020).
osteoarthritis (15 papers, 2008 to 2025). A noninflammatory degenerative joint disease occurring chiefly in older persons, characterized by degeneration of the articular cartilage, hypertrophy of bone at the margins and changes in the synovial membrane. "Specifically, CBD, CB1 agonists, CB2 agonists, as well as FAAH inhibitors, have been shown to reduce pain, allodynia, or nociceptive fiber firing in animal models of osteoarthritis." (PMID 41368581, 2025). "FAAH inhibitors have been reported to effectively reduce pain in rodent models of osteoarthritis by reducing inflammatory flares." (PMID 33986678, 2021). "FAAH inhibition as a treatment for patients with osteoarthritis pain showed no analgesic effect, compared with naproxen, in a phase II proof-of-concept study, despite promising findings in preclinical models and healthy volunteers." (PMID 28383710, 2017). "A recent clinical study of the FAAH inhibitor PF-04457845 in osteoarthritis pain showed a lack of analgesic efficacy despite demonstration of significant elevation of FAA in patients' plasma and significant efficacy in preclinical studies in rodent models of non-neuropathic pain." (PMID 24788435, 2014). "A potent and selective FAAH inhibitor, PF04457845, did not produce better anti-nociceptive effects than the placebo when investigated in a randomized placebo controlled clinical trial in patients with osteoarthritis." (PMID 32093166, 2020).